SATB2 (SATB homeobox 2)
Diseases named in the same sentence as SATB2 in open-access papers (continued):
Sharing a sentence is not in itself a finding about the gene and the disease.
neurodevelopmental disorder (13 papers, 2015 to 2025). A behavioral and cognitive disorder with onset during the developmental period that involves impaired or aberrant development of intellectual, motor, or social functions. "Mutations or structural variants affecting SATB2 result in SATB2-associated syndrome, a neurodevelopmental disorder characterised by ID, speech delay, and craniofacial anomalies." (PMID 41384038, 2025). "SATB2‐associated syndrome (SAS) is a neurodevelopmental disorder caused by heterozygous pathogenic variants in the SATB2 gene, and is typically characterized by intellectual disability and severely impaired communication skills." (PMID 34241948, 2021). "This leads us to suggest that reduced dosage of either MBD5 or SATB2 causes neural stem cells to be more characteristic of differentiating cells than proliferating cells, and that this may be a unifying feature of neurodevelopmental disorders more generally." (PMID 25966365, 2015). "A recent article has identified high frequency of de novo mutations or variants (DNMs) in few genes which include PURA, SATB2, SCN1A, and TUBA1A and these are mostly found in cases of neurodevelopmental disorders (NDDs)." (PMID 39263390, 2024). "SATB2 variants have been previously associated with SAS, SATB2-associated syndrome (OMIM#612313), a similar neurodevelopmental disorder." (PMID 34768579, 2021).
infection (9 papers, 2016 to 2026). The state of being infected such as from the introduction of a foreign agent such as serum, vaccine, antigenic substance or organism. "While it stands to reason that maternal vaccination against IAV before infection would similarly protect against SATB2 abnormalities in our model, this still needs to be tested." (PMID 38961232, 2025). "Lentiviral-mediated infection of SATB2 gene in PrECs (PrEC/SATB2) resulted in an increased expression of SATB2 mRNA." (PMID 38891096, 2024). "The Cd90, Cd29 and Ki67 mRNA levels were increased by Ad‐Satb2 infection but reduced by Ad‐siSatb2 infection." (PMID 33660290, 2021). "Cells infected with Ad‐Satb2 exhibited higher ALP activity on day 3 and 5 after infection than cells in the other groups, and the effect was dependent on the Ad‐Satb2 virus dose." (PMID 33660290, 2021). "Satb2 expression at both the mRNA and protein level increased in mouse incisor MSCs after infection with Ad‐Satb2 and decreased after infection with Ad‐siSatb2 compared with the control and endogenous level." (PMID 33660290, 2021). "Lentiviral mediated infection of SATB2 gene in CRL-1831 (CRL-1831/SATB2) cells resulted in an increased expression of SATB2 mRNA and protein." (PMID 28887549, 2017). "Lentiviral-mediated infection of SATB2 gene in HPNE (HPNE/SATB2) cells resulted in an increased expression of SATB2 protein and mRNA, as tested by the Western blotting, RT-PCR and immunocytochemistry." (PMID 27472393, 2016). "To investigate whether the in utero infection impacted the number of callosal neurons, we used the isotropic fractionator method to estimate the total amount of cortical SATB2+ cells." (PMID 38140578, 2023). "However, infection of C2C12 muscle cells with an adenovirus expressing enhanced Cas9 led to a notable increase in SATB2 protein content in post-differentiated myoblasts, at a time when SATB2 would otherwise be in significant decline." (PMID 35326417, 2022). "We found Satb2 overexpression infected with Ad‐Satb2 slightly promoted Dmp1 and Dspp expression on day 3 and markedly upregulated on day 7, which was inhibited by knockdown of Satb2 expression with Ad‐siSatb2 infection." (PMID 33660290, 2021). "Interestingly, Satb2 mRNA expression was not induced after Ad‐Bmp9 infection, suggesting that Satb2 may not act as a direct target of Bmp9 osteogenic signalling." (PMID 33660290, 2021).
gastrointestinal tumors (6 papers, 2018 to 2025). "Our results show that the specific markers of gastrointestinal tumors, including CDX2 and SATB2, were consistently negative in SRCC, while Villin or COX2 had positive expression levels in one case, so this indicator needs to be carefully considered in the differential diagnosis." (PMID 37337182, 2023).
psychiatric disorder (4 papers, 2017 to 2025). A disorder characterized by behavioral and/or psychological abnormalities, often accompanied by physical symptoms. "Rsp- or CA1-specific Cre is needed to exclusively delete Satb2 for elucidating its function in these regions, which will promote our understanding of how Satb2 is involved in neurodevelopmental diseases and psychiatric disorders." (PMID 31666685, 2020). "Hence, interactions between SATB2 and the inner nuclear membrane protein LEMD2 influence gene expression programs in pyramidal neurons that are linked to cognitive ability and psychiatric disorder etiology." (PMID 33319920, 2021). "Given the highly significant overlap in the transcriptional profiles of SATB2‐deficient and LEMD2‐depleted cortical neurons, we set out to investigate whether LEMD2‐regulated gene set contributes to human psychiatric disorders and cognitive phenotypes." (PMID 33319920, 2021).
colorectal (2 papers, 2012 to 2024). "Altogether, these data indicate an important role for SATB1 in colorectal carcinogenesis and suggest prognostically antagonistic effects of SATB1 and SATB2." (PMID 22935204, 2012).
SATB2 also shares sentences with these, for which no sentence is quoted: gastric adenocarcinoma (3 papers); ankyloglossia (2); behavioral disorders (2); cholangiocarcinoma (2); chondroblastoma (2); dysplasia (2); esophageal adenocarcinoma (2); laryngeal carcinoma (2); laryngeal squamous cell carcinoma (2); learning disabilities (2); leiomyoma (2); leiomyosarcoma (2); Microdeletion Syndrome (2); Micrognathia (2); nervous system diseases (2); oral squamous cell carcinoma (2); Pierre-Robin sequence (2); Rett syndrome (2); ulcerative colitis (2); uterine carcinosarcoma (2); acute myeloid leukemia (1); adenosarcoma (1); Alzheimer disease (1); angiosarcoma (1); appendiceal neoplasm (1); attention deficit-hyperactivity disorder (1); autoimmune disease (1); Barrett's oesophagus (1); bile duct adenocarcinoma (1); bile duct tumor (1).
A further 69 diseases each share a sentence with SATB2 in 1 paper.